MITF (melanocyte inducing transcription factor)
Diseases named in the same sentence as MITF in open-access papers (continued):
Sharing a sentence is not in itself a finding about the gene and the disease.
melanoma (continued). "We confirmed that a fraction of CFSE‐labelled patient melanoma cells also expressed varying levels of MITF and/or SOX10 along their migration path, indicating that melanoma ITH was preserved after implantation." (PMID 36692026, 2023). "In contradiction with this reasoning, 23% of relapsed melanomas show increased MITF expression, with two possible explanations: transcriptional plasticity, and MITF gene amplification correlated with disease progression." (PMID 37174072, 2023). "MITF is frequently amplified in melanoma, and its ectopic expression with BRAFV600E transforms normal melanocytes into immortalized melanocytes." (PMID 37658191, 2023). "Another study presented GTPs suppressed melanoma via regulating the circ_MITF/miR-30e-3p/HDAC2 axis." (PMID 37764768, 2023). "MITF plays the most relevant role in melanoma, by controlling the differentiation and proliferation of the melanocytes." (PMID 36676131, 2023). "The antigenicity of melanoma cells is significantly influenced by the proteins expressed by MITF target genes." (PMID 36747120, 2023). "In contrast, the pan melanoma cocktail and MITF stain showed positive staining in 86% and 93% of cases, respectively, for epithelioid cells, and 86% for spindle-shaped melanoma cells." (PMID 38132479, 2023). "Specifically, MITF is a member of the microphthalmia family of transcription factors and is dysregulated in melanoma." (PMID 36980194, 2023). "In our cohort, out of 115 patients referred to genetic counseling for melanoma, 25 tested positive (21.7%) for critical mutations: CDKN2A (n = 12), MITF (n = 3), BAP1 (n = 1), MC1R (n = 3), PTEN (n = 1), TYR (n = 2), OCA2 (n = 1), and SLC45A2 (n = 2)." (PMID 37568588, 2023). "High levels of MITF expression have been shown to favor a non-invasive, proliferative melanoma phenotype, while low levels of MITF expression favor an invasive, metastatic melanoma phenotype." (PMID 37626741, 2023). "We discovered that TG2 expression is required during the process of melanoma pigmentation by modulating MITF expression and activity." (PMID 37898636, 2023). "In some instances, cells depended strongly on the lineage factor, for example PAX8 in RCC, MITF in melanoma, and IRF4 in multiple myeloma (MM)." (PMID 37554444, 2023). "The most dynamic trend of MITF in melanoma is the transition to a mesenchymal phenotype and to enhance autophagy in response to a variety of tumor microenvironmental stresses." (PMID 37370757, 2023). "MITF expression is conserved in primary and metastatic malignant melanomas and is imperative in distinguishing cutaneous melanomas from nonmelanocytic lesions." (PMID 36834926, 2023). "In the case of sporadic melanomas, comprising more than 90% of all melanomas, several susceptibility loci acting as moderate (BAP1, TERT, POT1, ACD, TERF2IP and MITF) or low penetration genes have been identified." (PMID 36765773, 2023). "The expression of AXL is inversely related to that of MITF, so that MITFhigh/AXLlow (proliferative) and MITFlow/AXLhigh (invasive) populations contribute mostly to intratumor heterogeneity in melanoma and, thereby, resistance to therapy." (PMID 37898636, 2023). "MITF amplification was found to be more prevalent in metastatic disease and correlated with decreased overall survival rates in melanoma patients." (PMID 38065972, 2023). "It has been found, however, that USP13 also stabilizes MITF, an oncogenic protein that plays a role in melanoma development by increasing MITF de-ubiquitination, subsequently resulting in reduction of MITF proteasome-mediated degradation." (PMID 36732432, 2023).
melanoma (continued). "The path of MITF research continues with MITF amplification in melanoma cell lines, which is correlated with increased sensitivity to chemotherapy." (PMID 37504268, 2023). "Eleven clusters were annotated as tumor cells because they expressed high levels of melanoma-associated marker genes (MLANA, MITF, PRAME and SOX10)." (PMID 38065972, 2023). "Expression of GREB1 and MITF in benign nevi (N = 20) and primary melanoma tumors (N = 89) was analyzed by immunohistochemistry (IHC)." (PMID 37658191, 2023). "High GREB1 and MITF expression levels were observed in 7/63 cases (11.1%) and 31/63 cases (49.2%), respectively, of primary melanoma with a depth over 1.5 mm." (PMID 37658191, 2023). "While a decrease in MITF only moderately suppresses cell proliferation, high levels of transcription factor are observed in more proliferative and less invasive melanoma cells." (PMID 37371034, 2023). "Strong selection by Fst and π ratio enriched canonical Wnt signaling pathway (GO:0060070) and Melanoma (ko05218), identifying MITF, a common gene adapted to ultraviolet radiation in the plateau." (PMID 36707771, 2023). "In this model, a lower expression of MITF represents reduced melanoma cell proliferation together with increased migration and invasion, and a higher expression of MITF denotes the proliferation of melanoma cells." (PMID 36675114, 2023). "The melanoma cell lines were classified as proliferative or invasive based upon their MITF/AXL expression activity." (PMID 36251678, 2023). "MITF expression is also correlated to the invasive capacity of melanoma cells and regulates the transition between proliferative and invasive states (“phenotype switching”)." (PMID 37627054, 2023). "Among transcription factors, microphthalmia-associated transcription factor (MITF), a member of the MiT family of bHLH-leucine zipper transcription factors, plays an important role in melanoma onset and progression." (PMID 37160873, 2023). "Nrf2-mediated down regulation of pigmentation markers (melanoma antigens) due to MITF inhibition promote a dedifferentiated melanoma cell that can escape from immune recognition." (PMID 36747120, 2023). "In this study, MITF-low zebrafish melanoma cells had striking transcriptional similarities to invasive melanoma signatures found in humans following treatment with small molecule inhibitors of MEK or BRAF." (PMID 37021774, 2023). "MITF regulates the expression of genes critical for the survival of melanocytes and melanoma cells, such as the anti-apoptotic proteins BCL2 and BCL2A1 and the cell cycle regulator CDK2." (PMID 36834926, 2023). "More specifically, during glucose deprivation, melanoma cells decrease MITF expression, and become invasive." (PMID 36675114, 2023). "As overexpression of MITF is shown to increase E-cadherin expression, while directly repressing CDH2 (N-cadherin), MITF downregulation results in cadherin switching in melanoma." (PMID 37181747, 2023). "The increased nuclear β-catenin levels promote MITF expression, which ultimately leads to the proliferation of melanoma cells and an increase in melanin production." (PMID 37299026, 2023). "Here, we aimed to explore the complex mechanisms behind the MITF/SOX10‐controlled RTK‐induced drug resistance in melanoma." (PMID 36251678, 2023). "Noticeably, 195 TFs were identified among the SEs predicted target genes, including SOX10 and MITF, master drivers of the melanocytic lineage, and well‐established transcriptional dependency of melanoma." (PMID 37408506, 2023). "Together, these results demonstrate that the intrinsic sensitivity of melanoma cells to IFNγ, T cells, and PD-1 blockade correlates with their ability to show a dynamic MITF response." (PMID 36812891, 2023).
melanoma (continued). "While down-regulation of MITF leads to an invasive phenotype, the loss of ZEB2 in melanocytes leads to dedifferentiation, and in melanoma cells results in increased ZEB1 expression, repressing E-cadherin, and contributing to progression and metastasis." (PMID 36675114, 2023). "In melanoma cells, the development of acquired resistance is attributed to the downregulation of MITF." (PMID 37370757, 2023). "α-MSH/MC1R/cAMP axis converges to the regulation of MiTF expression with a pivotal role for homeostasis but when impaired in melanoma environment it takes a role in tumor progression and survival." (PMID 37608347, 2023). "The same study also showed that resistant melanomas possess low MITF expression, but high levels of inflammatory nuclear factor ‘kappa-light-chain-enhancer’ of activated B-cells (NF-ĸB) signaling and the receptor tyrosine kinase (RTK) AXL." (PMID 36675114, 2023). "MITF is an important survival factor for melanoma, and changes in its expression levels can have major consequences in several contexts." (PMID 36812891, 2023). "Trametinib-resistant cells displaying a dedifferentiation phenotype were less responsive presumably due to the already low level of MITF, a master regulator of the melanoma phenotype." (PMID 37175614, 2023). "An increase in MITF expression in melanoma cells is considered a sign of disease progression, among other things, due to its ability to activate the expression of anti-apoptotic proteins and pro-survival functions." (PMID 37371034, 2023). "Studies supporting SOX10 as a more sensitive marker for melanoma, compared to MITF, the previous standard marker for neoplastic testing within this sector, further highlight its diagnostic potential." (PMID 38132479, 2023). "The microphthalmia-associated transcription factor MITF is a lineage-survival oncogene that plays a crucial role in melanocyte development and melanoma." (PMID 37770430, 2023). "For example, the PAX3/MITF/PGC1α axis promotes MAPKi tolerance in a subset of melanoma cells through a mitochondria-mediated metabolic shift." (PMID 37616051, 2023). "As a result, GTPs suppressed melanoma progression by regulating the circ_MITF/miR-30e-3p/HDAC2 axis, revealing a potential therapeutic strategy for the human malignant melanoma intervention." (PMID 36829966, 2023). "A study of melanoma cells exposed to UV light found that BRG1 inhibited apoptosis alongside MITF to permit transcription of the melanoma inhibitor of apoptosis promoter ML-IAP." (PMID 36769189, 2023). "As a result, melanoma cells expressing low levels of MITF and high BRN2 (MITFlow/BRN2high) are demonstrated to be significantly more tumorigenic than MITFhigh/BRN2low cells when injected subcutaneously into mice." (PMID 37181747, 2023). "MITF coordinates many different signaling pathways in melanoma, including cell-cycle regulation, differentiation, and migration, depending on its expression levels." (PMID 37762707, 2023). "Compared to melanomas with high levels of MITF expression (MITF-high), MITF-low melanomas are shown to be more invasive." (PMID 37239381, 2023). "Conversely, overexpression of wild-type (WT) MITF in non-melanoma 293T cells increased GREB1 Is4, PMEL, and MLANA mRNAs." (PMID 37658191, 2023). "LN metastasis requires that melanoma cells to undergo a metabolic shift towards FAO induced by MITF, a key transcription factor in MYC+MEL cells." (PMID 38065972, 2023). "The clinicopathological parameters of melanoma cases with high GREB1 or MITF expression were compared to those with low GREB1 or MITF expression." (PMID 37658191, 2023). "We therefore established a 501mel human melanoma cell line stably expressing doxycycline-inducible HALO-tagged MITF WT and K206 mutants." (PMID 37770430, 2023). "Univariate analysis of in-house melanoma cases demonstrated that pStages III and IV and high MITF expression are significantly associated with shorter overall survival." (PMID 37658191, 2023).
melanoma (continued). "MITF has been extensively studied in melanoma cells where its transcriptional activity modulates target genes involved in pigmentation, such as TYR, MC1R, DCT, and MLANA." (PMID 37898636, 2023). "Although raised from different cells, mastocytosis and melanoma share factors such as MITF, STAT3, and dependence on KIT signaling, suggesting some similarities in both pathologies." (PMID 36834926, 2023). "As MITF is a central regulator of melanoma phenotype switching, we analyzed MITF responsiveness to alternating periods of trametinib withdrawal and rechallenge." (PMID 37175614, 2023). "Altogether, these findings suggest that MITF can also dictate the melanoma phenotype through lipid metabolism regulation." (PMID 35406721, 2022). "Current evidence suggests that MITF is closely related to mitochondrial energy metabolism in melanoma." (PMID 36620597, 2022). "The MITF (melanocyte-inducing transcription factor)-rheostat model incorporates the six different phenotypic states found in melanoma to date." (PMID 35903095, 2022). "Upregulation of the MITF/PGC-1α in melanomas promotes mitochondrial energy metabolism and a concomitant increase in ROS detoxification capacity, that enable cancer cells to withstand oxidative damage and to survive under stressful conditions." (PMID 36077374, 2022). "It has been demonstrated that MiTF is an amplified oncogene in a fraction of human melanomas and that it also has an oncogenic role in human clear cell sarcoma." (PMID 35531069, 2022). "This cut‐off was chosen since the top and bottom 25% of melanomas ranked by MITF include the highest and lowest melanomas exhibiting an invasive gene expression signature and exclude those where the invasive signature is not changing substantially." (PMID 35771179, 2022). "Multiple studies have affirmed the positive regulation of MITF transcription by CREB1 in malignant melanoma." (PMID 36268034, 2022). "Several studies on melanoma and RCC identified accelerated tumour progression and poor clinical outcome by improving the transcriptional activity of MITF upon mutating its SUMOylation residues." (PMID 35452181, 2022). "MITF itself is a master regulator of melanocyte differentiation, has anti‐apoptotic properties in melanoma and increases cellular survival." (PMID 34951143, 2022). "Lately, the TCGA analysis of the melanoma gene expression signatures also found the MITF low group, the immune group and the keratin groups." (PMID 35628196, 2022). "Two crucial transcription factors, microphthalmia-associated transcription factor (MITF) and SRY-box transcription factor 10 (SOX10), important in melanoma development and progression, have been implicated in this process." (PMID 36040798, 2022). "Melanoma cells expressing MITF at a high level can either differentiate or proliferate; however, low activity of MITF is related to stem cell-like or invasive potential." (PMID 35883768, 2022). "MITF represents a melanocytic lineage-specific transcription factor, which has a function that is directly correlated to malignant melanoma." (PMID 35565234, 2022). "In line with our results, Gaddameedhi’s lab recently reported that MITF shows a rhythmic expression via BMAL1 interaction with the MITF promoter in human melanoma cells." (PMID 35562405, 2022). "In total, these data demonstrate that MITF mediates the influence of Wnt/β-catenin signaling on ferroptosis in melanoma." (PMID 36429010, 2022). "MITF in melanoma not only acts as a major oncogene, but also correlates with many lysosomal genes and generates late endosomes that are not functional in proteolysis." (PMID 35563798, 2022). "SOX10 is essential for melanocytes and highly expressed in melanoma; it directly binds to the MITF promoter to upregulate MITF expression and activates PGC-1α to promote mitochondrial oxidative phosphorylation." (PMID 36620597, 2022).
melanoma (continued). "The MITF gene is expressed in different isoforms in which MITF-M (here referred as MITF) is exclusively expressed in melanocyte/melanoma cells and acts as a transcription factor controlling melanocyte development, survival, and differentiation." (PMID 35580987, 2022). "The inhibition of NOX with DPI decreased ROS production, inhibited cell growth, promoted cell differentiation of B16 melanoma cells, and increased MITF expression." (PMID 35326089, 2022). "Upregulated MITF expression is related to inherent B-Raf inhibitor resistance, and MITF amplification is associated with BRAF-positive melanomas." (PMID 36143375, 2022). "SMARCA4 was found to regulate MITF expression and to interact with MITF in melanoma cells, thereby promoting expression of an extensive number of pigmentation genes." (PMID 35323214, 2022). "Most biopsy samples of melanoma patients and drug-sensitive melanoma cell lines have shown increased expression of MITF." (PMID 36224606, 2022). "Collectively, these findings established that targeting Wnt/β-catenin signaling exacerbates ferroptosis in melanoma via the regulation of MITF." (PMID 36429010, 2022). "Goding and colleagues have introduced a rheostat model, according to which MITF expression levels determine the phenotypic state of melanoma cells within the phenotype switching process." (PMID 35693944, 2022). "A regulatory loop between Rec and MITF inhibits epigenetic phenotype switching between proliferative and invasive melanoma states." (PMID 36497341, 2022). "MITF is a transcription factor specific for melanocytic lineage which regulates many biological processes in melanocytes and melanoma cells." (PMID 35055021, 2022). "The most updated model of phenotypic plasticity in melanoma includes 6 cell states, including 2 with low expression of MITF." (PMID 36040798, 2022). "Collagen abundance and stiffness were shown to promote the nuclear localization of YAP, which regulated melanoma cell pigmentation and differentiation through the expression of MITF." (PMID 36119516, 2022). "In melanocytes/melanoma, MITF interacts with β-catenin and redirects β-catenin-mediated transcriptional activity from canonical Wnt/β-target genes to specific MITF target genes to activate their transcription." (PMID 35158973, 2022). "For example, a single-cell study in melanoma showed that two distinct transcriptional cell states, characterized by high levels of MITF expression and low MITF expression with elevated levels of AXL kinase, coexist in the same tumor." (PMID 34405376, 2022). "Here, we applied tamoxifen-inducible creERt2/loxP lineage tracing to a zebrafish model of MITF-dependent melanoma regression and recurrence to image and trace cell populations in vivo through disease stages." (PMID 35929478, 2022). "We tested 3 MITF-methylated melanoma cultures, and stable SOX10KO clones were generated exclusively in the MM383 cell line." (PMID 36040798, 2022). "A low MITF/AXL ratio predicts early resistance to multiple targeted drugs in melanoma, further linking dormancy mediating signals to melanoma plasticity." (PMID 35565234, 2022). "In melanoma, MITF is essential for cell proliferation and differentiation via regulating multiple genes transcription." (PMID 35445009, 2022). "In melanoma cell biology, MITF is a central player, controlling aspects of phenotypic switching, and is one of several critical transcriptional regulators involved in melanocyte development, upregulating a set of genes to drive melanocytic differentiation." (PMID 36248850, 2022). "It has been previously reported that RAF and MEK inhibitors can increase the expression of MITF and MITF targets in human melanoma cell lines." (PMID 35580987, 2022).